COP1 (COP1 E3 ubiquitin ligase)
Diseases named in the same sentence as COP1 in open-access papers (continued):
Sharing a sentence is not in itself a finding about the gene and the disease.
diabetes (2 papers, 2021). "Cop-1 also seems to carry potential, and it is the only DMD with a study involving comorbid animals, with diabetes mellitus in particular." (PMID 33562264, 2021).
multiple myeloma (2 papers, 2015 to 2021). "Further, high expression of Aurora A was associated with poor overall survival in multiple myeloma, and COP1 expression was positively correlated with Aurora A expression in cancer as evident in multiple cancer data set studies." (PMID 25957415, 2015).
non-small cell lung carcinoma (2 papers, 2017 to 2021). A group of at least three distinct histological types of lung cancer, including non-small cell squamous cell carcinoma, adenocarcinoma, and large cell carcinoma.
Obesity (2 papers, 2021 to 2024). Accumulation of substantial excess body fat. "The development of drugs that suppress the expression of Trib3 through the transcriptional regulation or activation of PKC, which specifically regulates COP1 activity, could be a potential strategy to prevent and treat diet- and aging-associated obesity and type 2 diabetes." (PMID 39623091, 2024). "Now, we await the results of experimental exploration of how altered TRIB/COP1 expression affects isoform-specific TRIB abundance, subcellular distribution and downstream functions—a pre-requisite for designing a range of TRIB/COP1-therapeutics to ameliorate obesity-related cancers." (PMID 34572744, 2021). "Unashamedly, the narrative is relayed through the perspective of the Tribbles Research and Innovation Network, and its establishment, progress and future ambitions: the growth of TRIB and COP1 research to hasten discovery of their cell-specific contributions to health and obesity-related cancers." (PMID 34572744, 2021).
prostate intraepithelial neoplasia (2 papers, 2015 to 2020). A neoplastic proliferation of the epithelial cells that line the acini and the ducts of the prostate gland. "In addition, COP1 deficiency increased cell proliferation, hyperplasia, and early prostate intraepithelial neoplasia by elevating ETV1 expression in mouse prostate." (PMID 25884720, 2015). "COP1 was found to play a tumor-suppressive role by degrading the oncogenic ETS transcription factors, and loss of COP1 promoted cell proliferation, hyperplasia, and early prostate intraepithelial neoplasia." (PMID 32660118, 2020). "Also, COP1 deficiency in mouse prostate elevated ETV1 and increased cell proliferation, hyperplasia, and early prostate intraepithelial neoplasia." (PMID 25884720, 2015).
prostate tumor (2 papers, 2020 to 2022). "We further found that COP1 mRNA levels were downregulated in collected prostate tumors, which was positively correlated with MAGI2-AS3 expression." (PMID 34976194, 2022).
Stroke (2 papers, 2015 to 2021). Sudden impairment of blood flow to a part of the brain due to occlusion or rupture of an artery to the brain. "In this study, diabetic mice were subjected to PMCAO and received Cop-1 for either 3 or 7 days after the stroke." (PMID 33562264, 2021). "The aim of this work was to evaluate the effect of Cop-1 on neurogenesis and neurological recovery during the acute phase (7 days) and the chronic phase of stroke (60 days) in a rat model of transient middle cerebral artery occlusion (tMCAo)." (PMID 25821957, 2015). "The aim of this study was to evaluate the effect of Cop-1 on neurogenesis and neurological recovery during the acute phase (7 days) and the chronic phase of stroke (60 days) in a rat model of tMCAo." (PMID 25821957, 2015). "In short, until 2015, two studies applying a model of TMCAO in rats supported that Cop-1 had potential in IS treatment, promoting neurogenesis and functional recovery, and reducing infarct volume in acute (seven days post-stroke) and chronic (60 days post-stroke) phases." (PMID 33562264, 2021). "Future studies will evaluate the optimal time window for Cop-1/GA treatment after stroke." (PMID 25821957, 2015).
Alzheimer disease (1 paper, 2022). A progressive, neurodegenerative disease characterized by loss of function and death of nerve cells in several areas of the brain leading to loss of cognitive function such as memory and language. "CEBPB was up-regulated in patients with Alzheimer’s disease, which increased the expression of pro-inflammatory genes in microglia, and the ubiquitin ligase COP1 inhibited neuroinflammation by silencing CEBPB in microglia." (PMID 35204186, 2022).
Cerebral ischemia (1 paper, 2023). Restriction of arterial blood supply to the brain associated with insufficient oxygenation to support the metabolic requirements of the tissue. "These outcomes were supported by further studies that evaluated the influence of Cop-1 administration in the production of neurotrophic factors and anti-inflammatory cytokines in the choroid plexus after cerebral ischemia using the tMCAo model." (PMID 36979898, 2023). "Another well-known NDP is Glatiramer acetate (also known as Cop-1, Copolymer 1 or Copaxone), a synthetic polypeptide constituted by tyrosine, glutamate, alanine, and lysine, which has been used in animal models for cerebral ischemia." (PMID 36979898, 2023).
colorectal tumors (1 paper, 2026). "Using an organoid biobank derived from paired primary colorectal tumors and liver metastases, integrated multi-omics analyses (WES, bulk RNA-seq, scRNA-seq) of patient-derived organoids (PDOs) from CRLM revealed significantly elevated COP1 expression in liver metastases compared to primary tumors." (PMID 41937206, 2026).
Fulminant hepatitis (1 paper, 2024). Acute hepatitis complicated by acute liver failure with hepatic encephalopathy occurring less than 8 weeks after the onset of jaundice. "Previous studies have reported implications of MDM2 and COP1 that targeted STAT3 for degradation in tumorigenesis, and involvement of MDM2 in RACK1-abrogated HDAC1 degradation during the pathogenesis of fulminant hepatitis." (PMID 39024388, 2024).
graft versus host disease (1 paper, 2012). An immune system disorder that occurs after allogeneic hematopoietic stem cell transplant and is a reaction of donor immune cells against host tissues. "In particular the study on graft-versus-host disease suggests that Cop-1, and hence GA, may act as a general immunomodulatory compound not requiring a role of MBP in the inflammatory response." (PMID 23203082, 2012).
hCMV infection (1 paper, 2021). "Not surprisingly, COP1 appears to be exploited by many viruses throughout their life cycles and has recently been shown to be required for hCMV infection using an siRNA screen similar to the one described here." (PMID 33975940, 2021).
Hepatic steatosis (1 paper, 2026). Steatosis is a term used to denote lipid accumulation within hepatocytes. "A recent study demonstrated that COP1 induces non-alcoholic fatty liver disease (NAFLD), a precursor to HCC, in normal hepatocytes and that reducing COP1 expression significantly improves high-fat diet-induced hepatic steatosis." (PMID 41940593, 2026).
hypoglycaemia (1 paper, 2021). "The relationship between COP1 and PEA3 members was also found to be important in regulating insulin secretion from pancreatic β cells, whereby hypoglycaemia caused by loss of Cop1 could be rescued by deletion of PEA3 family members in a mouse model." (PMID 34066106, 2021).
immune deficiency (1 paper, 2023). "It is proved that COP1 can alleviate immune deficiency by activating the MAPK signaling pathway." (PMID 36846714, 2023).
insulinoma (1 paper, 2021). "Depleting COP1 or DET1 leads to the accumulation of ETV5 and, to a mild extent, ETV4 in MIN6 insulinoma cells, whereas co-expressing COP1 and DET1 diminishes ETV5 levels, suggesting that CRL4COP1/DET1 mediates ETV5 degradation, which is further supported by ETV5 stabilization upon MLN4924 treatment." (PMID 33911083, 2021).
ischemia (1 paper, 2021). A hypoperfusion of the BLOOD through an organ or tissue caused by a PATHOLOGIC CONSTRICTION or obstruction of its BLOOD VESSELS, or an absence of BLOOD CIRCULATION. "The prospect of neuronal regeneration, which Cop-1 seems to support, is particularly important for ischemia, where neurons die and recovery prospects are thus diminished." (PMID 33562264, 2021).
lentivirus infection (1 paper, 2015). Virus diseases caused by the Lentivirus genus. "To confirm their potential function link, we constructed COP1 overexpression MDA-MB-231 strains by lentivirus infection." (PMID 25884720, 2015).
lymph node metastasis (1 paper, 2015). "COP1 expression status was associated with TNM stages of TNBCs, lymph node metastasis and tumor relapse." (PMID 25884720, 2015).
metastatic melanoma (1 paper, 2025). A melanoma that has spread from its primary site to another anatomic site. "In this report, we identify an increase in constitutive photomorphogenic 1 (COP1; RFWD2) as the mediator of increased apoptosis and inhibition of metastatic pulmonary melanomas in the syngeneic B16F10 murine model of metastatic melanoma." (PMID 40562100, 2025).
osteosarcoma (1 paper, 2017). A usually aggressive malignant bone-forming mesenchymal neoplasm, predominantly affecting adolescents and young adults.
Sepsis (1 paper, 2007). Sepsis is defined as life-threatening organ dysfunction caused by a dysregulated host response to infection. "With regard to apoptosis, both pro-apoptotic (COP1, GADD45B and RIPK2) and anti-apoptotic (TNFAIP3 and BIRC3) genes were induced in the early stages of sepsis." (PMID 17324256, 2007).
triple-negative breast carcinoma (1 paper, 2015). An invasive breast carcinoma which is negative for expression of estrogen receptor (ER), progesterone receptor (PR), and human epidermal growth factor receptor 2 (HER2). "However, the co-existing status of ETV1 and COP1 in triple-negative breast cancer (TNBC) and their predictive role in determining the patient’s outcome are uncertain." (PMID 25884720, 2015).
tumor (46 papers, 2010 to 2026). "This interaction is particularly relevant in the context of cancer biology, where COP1 has been implicated in tumor suppression by regulating transcription factors like c-Jun and oncogenic pathways." (PMID 41540009, 2026). "The expression of Cop1 promotes the secretion of macrophage-associated chemokines by tumor cells, which enhances macrophage infiltration within the tumor, particularly M2 macrophages." (PMID 39966355, 2025). "COP1, an E3 ubiquitin ligase, has been implicated in regulating tumor cell proliferation, apoptosis, and DNA repair." (PMID 40395328, 2025). "According to the data, deleting E3 ubiquitin ligase Cop1 in cancer cells leads to a decrease in macrophage-associated chemokines, a reduction in tumor macrophage infiltration, enhanced anti-tumor immunity, and a stronger ICI response." (PMID 38893132, 2024). "The increased expression of COP1 is associated with increased cell proliferation, cell transformation and tumor progression." (PMID 33670160, 2021). "In mice, the complete loss of COP1 function results in embryonic lethality, whereas studies of a partial loss of COP1 function have provided in vivo evidence of its tumor suppressor role." (PMID 30405104, 2018). "As a tumor suppressor, partial or tissue-specific loss of COP1 function causally contributes to tumorigenesis." (PMID 25884720, 2015). "Similarly, the stability of c-Jun is regulated by COP1, where COP1 is implicated as a tumor suppressor." (PMID 41540009, 2026). "COP1 ubiquitinates FASN to prevent excessive lipid accumulation, while mutations in SPOP impair FASN degradation, promoting tumor growth." (PMID 40370434, 2025). "Collectively, these findings demonstrate that COP1 suppresses ferroptosis and drives tumor progression in RCC in vivo, with ACSL4 downregulation and enhanced proliferation serving as critical mechanisms." (PMID 40395328, 2025). "Compared to the vector control group, tumors derived from COP1-overexpressing cells exhibited significantly increased tumor weight and volume." (PMID 40395328, 2025). "In vivo, COP1 overexpression accelerated tumor growth in xenograft models, with a 2.5-fold increase in tumor volume compared to controls (p < 0.001), accompanied by reduced ACSL4 expression and elevated Ki67 proliferation index." (PMID 40395328, 2025). "This study uncovers COP1 as a novel E3 ubiquitin ligase in RCC that targets ACSL4 for K48-linked ubiquitination and degradation, thereby suppressing ferroptosis and driving tumor progression." (PMID 40395328, 2025). "They demonstrated that the E3 ubiquitin ligase COP1 interacts with STAT3, mediating its ubiquitination and degradation, while miR-424 promotes STAT3 stabilization and activity, thereby facilitating tumor progression by targeting COP1." (PMID 40771930, 2025). "Functionally, this axis drives tumor progression by enhancing proliferation, migration, and invasion, while clinically, high COP1 expression correlates with aggressive disease features and poorer patient prognosis." (PMID 40395328, 2025). "The authors discovered that the deletion of E3 ubiquitin ligase Cop1 sensitised TNBC 4T1 tumours as well as the murine tumour models EMT6 (TNBC) and MC38 (colon) to immunotherapy." (PMID 37686639, 2023). "In patient #19, fifteen oncogenic mutations were CDX tumor-exclusive, affecting genes such as CDK8, COP1, and MAP2K2." (PMID 36980717, 2023). "Then, we stained 260 CRC tumor tissues by the IHC method to determine the protein expression of COP1 and UTX." (PMID 37679762, 2023).
tumor (continued). "As a result, targeting Cop1 improves the anti-tumor immune response and strengthens the response to immune checkpoint blockade." (PMID 37876793, 2023). "Targeting Cop1 and modulating chemokine secretion and tumor microenvironment macrophage infiltration improved TNBC cancer immunotherapy efficacy." (PMID 38003514, 2023). "Subsequently, we observed that Cop1−/+ mice displayed fewer macroscopic tumors and a low average tumor load than WT mice." (PMID 37679762, 2023). "Immunoblotting of six pairs of CRC tumors and adjacent normal tissues confirmed that COP1 expression was upregulated in CRC tumor tissues." (PMID 37679762, 2023). "In summary, mutation in COP1 was identified in all four CDXs from diverse tumor types suggesting COP1 as a potential driver of metastasis." (PMID 36980717, 2023). "COP1 appears to act as a tumour suppressor through the regulation of PEA3 member protein levels in various forms of cancer." (PMID 34066106, 2021). "The increased tumor burden formed by COP1 knockdown cells was significantly abrogated by APCP treatment, which was consistent with our observations of Ki-67 expression." (PMID 33168024, 2020). "Nevertheless, it makes sense that two potential oncoproteins, such as CSN6 and COP1, are involved in degrading a tumor suppressor FOXO4 to promote cell proliferation, survival, and cancer growth." (PMID 33101846, 2020). "Further characterization of in vivo models established the role of human COP1 as a tumor suppressor." (PMID 30482246, 2018). "COP1 expression promoted cell proliferation, cell transformation, and tumor progression, manifesting its role in cancer promotion, whereas 14-3-3ơ negatively regulated COP1 function and prevented tumor growth in a mouse xenograft model of human cancer." (PMID 27156963, 2016). "Either ETV1 or COP1 expression status was significantly associated with TNM stages of TNBC, the number of lymph nodes involved and tumor relapse." (PMID 25884720, 2015). "Notably, COP1 exhibits context-dependent roles in tumorigenesis, acting as either a tumor suppressor or promoter depending on its interacting targets." (PMID 40395328, 2025). "For example, COP1 may also play a tumor-suppressive role as it mediates the degradation of the oncoprotein c-Jun, which makes the therapeutic potential of COP1 inhibition uncertain at this time." (PMID 40002221, 2025). "Negative regulation of ETV1 can activate COP1 as a tumor suppressor in patients with TNBC." (PMID 34746770, 2021). "However, human cancer sample analyses indicate that COP1 is highly expressed in many types of cancer and that COP1 overexpression correlates with poor survival, conflicting with the idea that COP1 can be a tumor suppressor." (PMID 33101846, 2020). "The COP1 KO mouse model shows a surprising activity about COP1's tumor suppressor role." (PMID 33101846, 2020). "Therefore, depending on COP1’s target, this E3 ubiquitin ligase can serve as a tumor suppressor or an oncogene in different cancer types." (PMID 28218667, 2017). "Previous studies have proposed a role for COP1 as a tumor suppressor gene." (PMID 26871468, 2016). "In our study, 14-3-3σ inhibited COP1-mediated tumor growth in xenograft cancer mice." (PMID 25957415, 2015).